GPD1 (glycerol-3-phosphate dehydrogenase 1)
Diseases named in the same sentence as GPD1 in open-access papers (continued):
Sharing a sentence is not in itself a finding about the gene and the disease.
fatty liver (4 papers, 2021 to 2026). "It has been suggested that the fatty liver observed in all patients with GPD1 deficiency on ultrasonography or other imaging may result from excessive acylation of dihydroxyacetone phosphate (DHAP)." (PMID 40216993, 2025).
glioma (4 papers, 2020 to 2024). A benign or malignant brain and spinal cord tumor that arises from glial cells (astrocytes, oligodendrocytes, ependymal cells). "In the glioma model, cells expressing GPD1+ were predominantly found at the tumor margin of newly developing tumors, but their numbers decreased significantly in fully developed tumors." (PMID 38275375, 2023). "A high expression of GPD1 (glycerol-3-phosphate dehydrogenase 1) has been observed in glioblastoma and glioma and correlates with poor survival in renal cell carcinoma." (PMID 35486664, 2022). "Therefore, these tumor cells are considered as quiescent glioma stem cells which participate in tumor initiation as GPD1+ expressing cells at the tumor margin but transition to a quiescent state with a loss of GPD1+ expression in later tumor stages." (PMID 38275375, 2023). "Cytosolic Glycerol-3-phosphate dehydrogenase 1 (GPD1, EC 1.1.1.8) plays a pivotal role in regulating the Embden-Meyerhof glucose glycolysis pathway (E-M pathway), as well as in conditions such as Huntington’s disease, cancer, and its potential role as a specific marker for Dormant Glioma Stem Cells." (PMID 38898093, 2024). "Similarly, dormant glioma stem cells were proven to shunt glycolytic intermediates towards glycerol and phospholipid metabolism via the upregulation of the enzyme GPD1: this metabolic profile is crucial to withstand ROS and ultimately maintain the dormant compartment of glioma cells." (PMID 32932943, 2020). "Another contribution in this context is the detection of glycerol-3-phosphate dehydrogenase 1 (GPD1) in glioma stem cells but not in normal neural stem cells from an experimental glioma model." (PMID 38275375, 2023).
Obesity (4 papers, 2019 to 2025). Accumulation of substantial excess body fat. "Studies have found that GPD1 has a pro‐obesity effect, and the activity of GPD1 is enhanced in morbidly obese patients." (PMID 40631874, 2025). "Given the pro-obesity or anti-lipid accumulation activity of GPD1 it is difficult to propose a unified idea on the role of GPD1 in human obesity." (PMID 38689091, 2024). "Enhanced GPD1 activity has been observed in morbidly obese patients, and correlations between GPD1 expression and obesity, body mass index (BMI), and fat mass were found." (PMID 38689091, 2024). "There is a correlation between GPD1 expression and obesity, body mass index (BMI) and fat mass." (PMID 40631874, 2025). "There is evidence showing that GPD1 has pro-obesity effects." (PMID 38689091, 2024). "In addition, CRYAB overexpression up-regulated GPD1 (FC > 1.5, p < 0.05), and in a human obesity study, triglyceride synthesis was reduced and muscle mass was increased by growth factor receptor bound protein 14 (GRB14) and GPD1." (PMID 36613828, 2022). "Therefore, the exact roles of GPD1 in obesity, muscle function, and protection against oxidants have not been well established." (PMID 38689091, 2024).
glioblastoma (3 papers, 2021 to 2022). The most malignant astrocytic tumor (WHO grade IV). "GPD1 expression has been shown to be activated in early tumor development stages, such as those of glioblastoma." (PMID 33663535, 2021).
liver diseases (3 papers, 2020 to 2025). "Next-generation sequencing for metabolic and genetic liver diseases was conducted with the identification of the homozygous mutation c.895G>A in GPD1 gene resulting in the aminocidic substitution p.G299R." (PMID 32685347, 2020).
prostate carcinoma (3 papers, 2021 to 2024). A carcinoma that arises from epithelial cells of the prostate gland. "GPD1 has been reported to play an anti-cancer role in a variety of cancers, including bladder, breast, lung and prostate cancers." (PMID 39063036, 2024). "Our previous studies have found that in prostate cancer and lung cancer, GPD1 can enhance the anti-tumor effect of metformin, with G3P playing a major role in inhibiting tumor proliferation." (PMID 34098990, 2021). "Our previous study also found that the overexpression of GPD1 in prostate cancer and lung cancer cells inhibits the aerobic phosphorylation of mitochondria, which may be related to the deregulation of the hypoxia pathway." (PMID 34098990, 2021).
renal clear cell carcinoma (3 papers, 2021 to 2024). "Recently, it has been described that, in renal clear cell carcinoma, hypoxia induced GPD1 expression and decreased lipid production." (PMID 39407866, 2024).
bladder cancer (2 papers, 2022 to 2024). "To reveal the mechanism underlying GPD1-induced apoptosis of bladder cancer cells, we performed RNA-seq analysis of control 5637 cells, GPD1-OE 5637 cells and K120A GPD1-OE 5637 cells to identify the genes that are affected by GPD1." (PMID 35836291, 2022). "In bladder cancer, the activation of GPD1 by wedelolactone successfully decreased cancer cell viability by ~50% and reduced tumor weight by ~70% in xenograft models." (PMID 38689091, 2024). "WE is a well-characterized allosteric GPD1 activator and a promising small molecule to inhibit bladder cancer growth." (PMID 35836291, 2022). "Further investigation showed that GPD1 overexpression significantly promoted apoptosis in bladder cancer cells." (PMID 35836291, 2022). "In this study, we compared protein profiles in bladder cancer tissues and adjacent normal tissues by proteomics, from which we found that GPD1 protein levels were significantly downregulated in bladder cancer tissues." (PMID 35836291, 2022). "To determine the tissue expression pattern of GPD1 in human bladder tumors, we generated tissue microarrays containing 76 human bladder cancer samples (T1 stage = 24, T2 stage = 28, T3 stage = 14, T4 stage = 10)." (PMID 35836291, 2022). "In GPD1-overexpressing bladder cancer cell lines (T24 and 5637), we observed an increase in the levels of G3P and NAD+." (PMID 35836291, 2022). "Given the antitumor function of GPD1 in bladder cancer, there is considerable interest in discovering activators of the enzyme." (PMID 35836291, 2022). "In the MIBC cohort, low mRNA levels of GPD1 were also significantly correlated with decreased survival time for bladder cancer patients." (PMID 35836291, 2022). "In our study, lysoPC promoted Ca2+ influx through TRPV2 and apoptosis in bladder cancer cells, which was similar to the effect of GPD1 overexpression." (PMID 35836291, 2022). "We further examined the expression level of GPD1 in human bladder cancer cell lines (5637, T24, J82, and UMUC3) and a human urothelial epithelial cell line (SV-HUC-1)." (PMID 35836291, 2022). "Staining of these samples using a validated antibody for GPD1 revealed reduced GPD1 expression in tumor tissue compared to normal tissue, and GPD1 expression gradually decreased with bladder cancer progression." (PMID 35836291, 2022). "In this context, the expression of transient receptor potential vanilloid 2 (TRPV2), one of the key genes in the NOD-like receptor signaling pathway, was significantly increased in bladder cancer cells after GPD1 overexpression." (PMID 35836291, 2022). "This requires further studies to investigate whether these proteins are involved in the downregulation of GPD1 in bladder cancer." (PMID 35836291, 2022). "In this study, our data show that GPD1 expression is at a low level in bladder cancer." (PMID 35836291, 2022). "Based on the potential antitumor function of GPD1, the development of drugs that modulate GPD1 activity may provide a new therapeutic strategy for bladder cancer." (PMID 35836291, 2022). "Finally, we screened and obtained the allosteric agonist wedelolactone for GPD1, demonstrating that pharmacological activation of GPD1 is a potential therapeutic approach for bladder cancer." (PMID 35836291, 2022). "To test our hypothesis that GPD1 may have a cancer cell inhibitory effect, we established bladder cancer cell lines (5637, T24) stably expressing GPD1 via lentivectors transduction." (PMID 35836291, 2022). "The function of GPD1 on bladder cancer cells were confirmed through in vivo and in vitro assays." (PMID 35836291, 2022). "Taken together, our findings highlight GPD1 as a novel tumor suppressor in bladder cancer." (PMID 35836291, 2022). "Pharmacological activation of GPD1 is a potential therapeutic approach for bladder cancer." (PMID 35836291, 2022).
bladder cancer (continued). "Finally, wedelolactone, an allosteric GPD1 activator, was identified for the first time based on virtual screening and was shown to effectively inhibit bladder cancer growth in vitro and in vivo." (PMID 35836291, 2022). "This information gives us an insight that the allosteric activators of GPD1 we found in combination with metformin may be a better therapeutic strategy for bladder cancer." (PMID 35836291, 2022). "We demonstrate for the first time that GPD1 overexpression can inhibit bladder cancer growth." (PMID 35836291, 2022). "Here, we used proteomics to find that GPD1 expression was at low levels in bladder cancer tissues." (PMID 35836291, 2022). "The underlying mechanisms of GPD1 in cancer are still not well studied, especially in human bladder cancer." (PMID 35836291, 2022). "Therefore, WE activates endogenous GPD1 catalytic activity in bladder cancer cells." (PMID 35836291, 2022). "An in vivo study showed that loss of GPD1 catalytic activity did not inhibit bladder cancer growth." (PMID 35836291, 2022). "This study suggests that GPD1 may act as a novel tumor suppressor in bladder cancer." (PMID 35836291, 2022). "Together, these results suggest that GPD1 is expressed at low levels in bladder cancer tissues and may have antitumor functions, which prompted us to further explore the role of GPD1 in the development of bladder cancer." (PMID 35836291, 2022). "We found that GPD1 promotes cellular Ca2+ influx, leading to apoptosis through the lysoPC-PAFR-TRPV2 signaling axis in bladder cancer cells." (PMID 35836291, 2022). "GPD1 mRNA levels in tumor tissues were not significantly different from those in normal tissues in bladder cancer cohort from TCGA datasets." (PMID 35836291, 2022). "RT-qPCR analysis showed that GPD1 mRNA levels in bladder cancer cells were not lower than in SV-HUC-1 normal cells." (PMID 35836291, 2022). "Consistent with our analysis of human bladder cancer tissues, the protein levels but not mRNA levels of GPD1 expression were significantly lower in bladder cancer cells than in SV-HUC-1 normal cells." (PMID 35836291, 2022).
Cirrhosis (2 papers, 2020 to 2022). A chronic disorder of the liver in which liver tissue becomes scarred and is partially replaced by regenerative nodules and fibrotic tissue resulting in loss of liver function. "Furthermore, cirrhosis developing at such a young age in some children opposes the prevailing perception of GPD1 being a benign or transient disease." (PMID 36051699, 2022).
diabetes (2 papers, 2021 to 2023). "In the present study, we observe that in diabetes, expression ofglycerol-3-phosphate dehydrogenase 1 (Gpd1) is significantly upregulated in BMVs while itis not changed in RMVs." (PMID 36606460, 2023). "Alternatively, GPD1 is oriented toward the transformation from DHAP into G3P under physiological conditions, when this process was impaired, the accumulation of DHAP could induce over production of methylglyoxal, a celluarly highly toxic compound, which leads to renal fibrosis in diabetes patients." (PMID 33907148, 2021).
Insulin resistance (2 papers, 2022 to 2023). Increased resistance towards insulin, that is, diminished effectiveness of insulin in reducing blood glucose levels. "Therefore, Mrap, Gpd1, Irs1 and Myc appear to play key roles in transmitting the Pparg signal to promote the AT expansion and concomitant insulin resistance in females, upon the loss of ovarian function." (PMID 36768630, 2023).
bladder tumors (1 paper, 2022). "Finally, we performed a virtual screening to obtain the GPD1 allosteric activator wedelolactone and demonstrated its ability to inhibit bladder tumor growth in vitro and in vivo." (PMID 35836291, 2022). "The colony formation assay indicated that GPD1 overexpression in 5637 cells and T24 cells significantly decreased the colony number, additionally supporting the growth inhibitory effect of GPD1 on bladder tumor cells." (PMID 35836291, 2022).
breast invasive carcinoma (1 paper, 2017). "The results revealed that invasive breast carcinoma patients with reduced GPD1 mRNA have significantly reduced overall survival (p = 0.024), which is consistent with our meta-analyses of the microarray datasets." (PMID 29254166, 2017).
Brugada syndrome (1 paper, 2021). A genetically heterogeneous condition characterized by complete or incomplete right bundle branch block accompanied by ST elevation in leads V1-V3. "Subsequently, nine articles described extra 30 mutations of GPD1 gene associated with HTGTI, chylomicronemia syndrome, Brugada syndrome or low HDL cholesterol, respectively." (PMID 34484308, 2021).
COVID-19 (1 paper, 2023). A disease caused by infection with severe acute respiratory syndrome coronavirus 2. "These proteins either act as positive regulators of cell death (HBG1, HBB, HBD, and HBA1) or are involved in the cellular response to tumor necrosis factor (FABP4, GPD1, THBS1, ASS1, and PCK2), suggesting that apoptosis may be an important cause of heart failure in patients with COVID-19." (PMID 38087340, 2023).
dysferlinopathy (1 paper, 2024). "Our proteomic profiling reveals a notable decrease in cytoplasmic GPD1 levels, indicating a potential reduction in mitochondrial oxidation of NADH from the cytosol and its consequent impact on triglyceride metabolism in dysferlinopathy." (PMID 39350328, 2024).
fibrosis (1 paper, 2022). the formation of excess fibrous connective tissue in an organ or tissue in a reparative or reactive process. "In conclusion, the current study identifies a novel biological function of miR-409-3p that promotes cardiac fibrosis by directly targeting the downstream gene Gpd1." (PMID 36275896, 2022).
gastric cancer (1 paper, 2025). A primary or metastatic malignant neoplasm involving the stomach. "In gastric cancer cells, the proteins glycerol-3-phosphate dehydrogenase 1 (GPD1) and glycerol-3-phosphate dehydrogenase 1-like (GPD1L) drive aberrant lipid droplet accumulation, which subsequently elevates FSP1 expression, enhances resistance to ferroptosis, and promotes peritoneal metastasis." (PMID 40862825, 2025).
Huntington disease (1 paper, 2024). Huntington disease (HD) is a rare neurodegenerative disorder of the central nervous system characterized by unwanted choreatic movements, behavioral and psychiatric disturbances and dementia. "Notably, studies in yeast cells have illuminated the significant role of GPD1 in regulating mutant proteins, particularly in the context of Huntington’s disease." (PMID 38898093, 2024).
hyperphosphatemia (1 paper, 2023). Abnormally high level of phosphate in the blood. "Further, we found that G-3-P dehydrogenase 1 (Gpd1), a cytosolic enzyme that synthesizes G-3-P and oxidizes NADH to NAD+, is required for phosphate-stimulated G-3-P and FGF23 production and prevention of hyperphosphatemia." (PMID 36821389, 2023).
hypoparathyroidism (1 paper, 2023). Hypoparathyroidism is an endocrine disorder in which the parathyroid glands in the neck do not produce enough parathyroid hormone (PTH). "Second, we administered diphtheria toxin (DT) to Gpd1–/– and Gpd1+/+ mice with parathyroid-specific expression of the DT receptor to induce hypoparathyroidism." (PMID 36821389, 2023).
kidney cancer (1 paper, 2024). Primary or metastatic malignant neoplasm involving the kidney. "Subsequently, consistent studies have reported that GPD1 expression is significantly reduced in several other cancers, such as breast, lung, bladder, and kidney cancer, and that a low expression level of GPD1 is significantly correlated with a poor survival rate." (PMID 38689091, 2024). "These may include cancer types (e.g., ccRCC vs. non-ccRCC kidney cancer or bladder vs. kidney cancer), species (mouse vs. human), or experimental conditions (e.g., hypoxia, glycolysis, or dual knockdown of GPD1 and GPD1L)." (PMID 38689091, 2024).
lipid metabolism disorder (1 paper, 2022). "They explicitly showed primary dyslipidemia, a lipid metabolism disorder, in early infancy is caused by a monogenic variant in the GPD1 gene." (PMID 36051699, 2022).
lung adenocarcinoma (1 paper, 2017). A carcinoma that arises from the lung and is characterized by the presence of malignant glandular epithelial cells. "Furthermore, the reduced GPD1 mRNA levels were also correlated with decreased overall survival in lung adenocarcinoma patients (p = 0.023)." (PMID 29254166, 2017).
melanoma (1 paper, 2025). A malignant, usually aggressive tumor composed of atypical, neoplastic melanocytes. "The molecular and mechanistic link between GPD1-ELOVL6 with BRAF V600E in melanoma is yet to be established." (PMID 39795195, 2025). "The downregulation of GPD1 and ELOVL6 further highlighted LA’s suppressive impact on melanoma metabolic pathways critical for tumor progression and survival." (PMID 39795195, 2025).
osteosarcoma (1 paper, 2024). A usually aggressive malignant bone-forming mesenchymal neoplasm, predominantly affecting adolescents and young adults. "GPD1 KO significantly abolished G3P synthesis and increased the NADH/NAD+ ratio when the ETC was inhibited in 143B (osteosarcoma) and HeLa (adenocarcinoma) cells, consistent with all other studies showing G3P generation by GPD1." (PMID 38689091, 2024).
Stroke (1 paper, 2023). Sudden impairment of blood flow to a part of the brain due to occlusion or rupture of an artery to the brain. "Of note, an increased expression of the Cd38 transcript in NAD+ deficient mice suggests that after stroke Cd38 mRNA could act in concert with the Gpd1 transcripts from astrocytes to increase glucose availability." (PMID 36818562, 2023).
transient infantile hypertriglyceridemia (1 paper, 2018). "Transient infantile hypertriglyceridemia (HTGTI) is an autosomal recessive disorder caused by mutations in the glycerol-3-phosphate dehydrogenase 1 (GPD1) gene." (PMID 29940878, 2018).